INHBA (inhibin subunit beta A)
Diseases named in the same sentence as INHBA in open-access papers (continued):
Sharing a sentence is not in itself a finding about the gene and the disease.
breast carcinoma (continued). "We examined RNA expression of INHBA and related family members and signaling proteins in our breast cancer cell line panel." (PMID 35248133, 2022). "Taken together, the data confirmed that the INHBA gene was upregulated in breast cancer compared with normal samples." (PMID 36304286, 2022). "We compared INHBA mRNA expression among groups of breast cancer patients according to different clinicopathological factors in the bc-GenExMiner v4.7 database." (PMID 36304286, 2022). "Breast cancer patients with positive progesterone receptor and human epidermal growth factor receptor-2 showed an increased level of INHBA mRNA expression." (PMID 36304286, 2022). "Correlation of INHBA mRNA expression and clinicopathological factors in breast cancer (bc-GenExMiner v4.7)." (PMID 36304286, 2022). "Next, we analyzed the relationships between the protein expression of INHBA and clinicopathological features in breast cancer using the UALCAN cancer database." (PMID 36304286, 2022). "The INHBA protein was also highly expressed in primary breast cancer and closely related to the pathological stage." (PMID 36304286, 2022). "Next, we further explored the prognostic value of INHBA in breast cancer using the PrognoScan and Kaplan–Meier plotter database." (PMID 36304286, 2022). "We found that the sample size of INHBA protein expression was small (normal n = 18; breast cancer n = 125), and more proof was needed." (PMID 36304286, 2022). "Using Breast Cancer Gene-Expression Miner (bc-GenExMiner v4.7) tool and the UALCAN cancer database, we further evaluated the correlation of INHBA expression with clinicopathological factors in breast cancer." (PMID 36304286, 2022). "We first looked at IL6 and IL13Rα2, which have previously been reported to be regulated by INHBA in ovarian and breast cancers." (PMID 35248133, 2022). "Oncomine data showed that INHBA mRNA expression obviously increased in multiple cancers compared with normal tissue and particularly in breast cancer." (PMID 36304286, 2022). "Meanwhile, the UALCAN cancer database showed that INHBA protein was also overexpressed in primary breast cancer compared with normal tissues." (PMID 36304286, 2022). "The population expressing higher levels of INHBA and CD142 acquired myofibroblast characteristics upon TGF-β treatment and a myo-cancer-associated fibroblast profile in the presence of breast cancer cells." (PMID 36009475, 2022). "Correlation of INHBA mRNA expression and clinical prognosis in breast cancer with different clinicopathological factors by Kaplan–Meier plotter." (PMID 36304286, 2022). "To further understand the potential mechanisms of INHBA expression in cancer, we analyzed the correlation of INHBA expression and clinical prognosis in breast cancer patients with different clinicopathological factors by Kaplan–Meier plotter." (PMID 36304286, 2022). "Taken together, these results indicate that INHBA plays an important role in regulating the infiltration of immune cells, especially macrophages and CAFs, in the tumor microenvironment of breast cancer." (PMID 36304286, 2022). "Together, these results strongly suggested that INHBA is a novel prognostic-related biomarker in breast cancer." (PMID 36304286, 2022). "In summary, INHBA is an important regulator of immune cell infiltration and a valuable prognostic biomarker in breast cancer patients." (PMID 36304286, 2022). "Overexpression of INHBA mRNA was associated with worse OS and RFS in the basal subtype of breast cancer (p < 0.05)." (PMID 36304286, 2022). "In vitro experiments were performed to evaluate the role of INHBA in cell proliferation and invasion of breast cancer by using the CCK-8, EdU and transwell assays with MCF-7 cells exhibiting overexpression or knockdown of INHBA." (PMID 34889158, 2021). "Mechanically, blocking of Wnt/β-catenin pathway by XAV939 reversed the promotion effect of INHBA overexpression on breast cancer cells’ proliferation, migration and invasion." (PMID 34889158, 2021).
breast carcinoma (continued). "Our findings illustrate a new target and underlying mechanisms of breast cancer progression, which provide an effective target for the treatment and diagnosis of breast cancer, and extend the understanding mechanism-related functions of INHBA in breast cancer." (PMID 34889158, 2021). "Quantitative real-time polymerase chain reaction (qRT-PCR) was conducted to assess the expression of INHBA in breast cancer cell lines." (PMID 34889158, 2021). "In the present study, we also found that INHBA is simultaneously over-expressed in breast cancer tissues and cells." (PMID 34889158, 2021). "Based on the results of qRT-PCR, INHBA expression was higher in breast cancer cells than that in normal epithelial cells." (PMID 34889158, 2021). "With the development of sequencing technology, studies have discovered that INHBA is overexpressed in breast cancer tissues." (PMID 34889158, 2021). "Consistently, the results indicated that the expression level of INHBA was dramatically elevated in breast cancer cell lines compared to MCF-10A cells, especially in MCF-7 cells that were used in the subsequent experiments." (PMID 34889158, 2021). "By performing a series of bioinformatics analyses, we found that INHBA was notably up-regulated in breast cancer tissues." (PMID 34889158, 2021). "Recent studies have shown that overexpression of INHBA occurs in multiple types of cancers, including colorectal cancer, breast cancer, lung cancer, esophageal squamous cell carcinoma, and bladder cancer." (PMID 31827640, 2019). "In breast cancer, INHBA signaling promotes breast cancer metastasis by regulating IL13Rα2 expression." (PMID 31827640, 2019). "Our study showed that ASPM, INHBA, NUF2, ORC6, UBE2T and PKMYT1 are associated with cell proliferation, and the expressions of these genes were also elevated in our breast cancer tissue transcriptome." (PMID 31182966, 2019). "Most importantly, our data indicate that knocking down INHBA levels in breast cancer cells delays primary tumor growth, suppresses migration in vitro and inhibits the formation of lung metastases in vivo." (PMID 30805303, 2019). "In this study, we show that expression of the activin subunit INHBA is elevated in multiple cohorts of breast cancers, whereas FST is suppressed." (PMID 28583174, 2017). "In contrast to BMPs, elevated expression of the activin subunit INHBA predicts worse outcomes in patients with breast cancer and is consistent with our observation that FST prevents metastasis." (PMID 28583174, 2017). "Further, the analysis revealed that INHBA expression correlates negatively with the distant metastasis-free survival of breast cancer patients." (PMID 28721365, 2015). "We show that INHBA expression correlates negatively with the overall survival of high-grade breast tumors and metastasis-free survival of breast cancer patients." (PMID 28721365, 2015). "Together, these findings indicate that INHBA may potentially inhibit the immune response by regulating immune cell recruitment and activation in breast cancer." (PMID 36304286, 2022). "Notably, INHBA mRNA expression was significantly higher in 19 breast cancer datasets than in normal breast tissues." (PMID 36304286, 2022). "The INHBA expression level could also serve as predictors of treatment effect and prognosis of patients with early breast cancer." (PMID 36304286, 2022). "We then analyzed the prognostic potential of INHBA gene in breast cancer patients." (PMID 36304286, 2022). "Elucidation of the mechanism of action of INHBA in HER2+ basal breast tumors will also help to devise optimal strategies for potential therapeutic inhibition of INHBA to improve outcomes in patients with advanced basal subtype HER2+ breast cancer." (PMID 35248133, 2022). "Besides, higher protein expression of INHBA was also found in primary breast cancer compared with normal tissues in the UALCAN cancer database." (PMID 36304286, 2022).
breast carcinoma (continued). "The purpose of our study was to explore the role of INHBA in breast cancer." (PMID 34889158, 2021). "In addition, the disruption of Wnt/β-catenin signaling by XAV-939 treatment reversed the stimulative effect of INHBA overexpression on breast cancer cell proliferation, migration and invasion." (PMID 34889158, 2021). "Our findings emphasized that INHBA may act as an oncogene via activating the Wnt/β-catenin pathway, which may provide a potential therapeutic target for the treatment of breast cancer." (PMID 34889158, 2021). "However, little is known as to how INHBA regulates the progression and aggressiveness of breast cancer (BC)." (PMID 34346300, 2021). "Wnt/β-catenin signaling pathway plays an essential role in cancer progression, and we speculated that INHBA facilitated breast cancer progression through Wnt/β-catenin signaling pathway." (PMID 34889158, 2021). "•INHBA was un unfavorable factor upregulated in BC (breast cancer) tissues and cells." (PMID 34346300, 2021). "Mechanistically, we elucidated the mechanism of INHBA in the breast cancer progression and indicated that it could regulate breast cancer cell invasion and EMT through Wnt/β-catenin signaling pathway." (PMID 34889158, 2021). "We then focused on exploring the functions of INHBA in the progression of breast cancer and demonstrated that inhibition of its expression could markedly attenuate the proliferation and epithelial–mesenchymal transition (EMT) of breast cancer cells." (PMID 34889158, 2021). "The result showed that INHBA was highly expressed in breast cancer cell lines." (PMID 34889158, 2021). "Our data presented here also demonstrate that shRNA-mediated depletion of INHBA in metastatic breast cancer cells led to suppression of IL13Rα2 mRNA and protein levels, whereas treatment of non-metastatic cells with Activin A resulted in upregulation of IL13Rα2 expression." (PMID 30805303, 2019). "Microarray study done in our laboratory revealed INHBA and various other genes involved in the activin signaling pathway to be differentially expressed in breast cancers (invasive ductal carcinoma) compared with normal tissue samples, suggesting activation of this signaling pathway." (PMID 28721365, 2015). "Although its role in breast cancer remains unclear, circulating levels of INHBA has been shown to be higher in breast cancer patients with bone metastasis." (PMID 19187537, 2009). "However, the expression of INHBA was not significantly correlated with stages of breast cancer, tumor mutational burden (TMB), and microsatellite instability (MSI)." (PMID 41008625, 2025). "In addition, we analyzed the correlation between INHBA expression and breast cancer prognosis by Kaplan–Meier, and results showed that patients with high INHBA expression had short overall survival (OS), recurrence-free survival (RFS), and distant metastasis-free survival (DMFS)." (PMID 41008625, 2025). "Results showed that INHBA gene expression was significantly up-regulated in breast tumor tissues compared to normal breast tissues, and the same results were observed across all pathological types of breast cancer, including Basal, HER2+, Luminal-A, and Luminal-B types." (PMID 41008625, 2025). "Meanwhile, the methylation level of the INHBA gene promoter was significantly reduced in breast cancer (data not shown), suggesting that the upregulation of INHBA gene expression in breast cancer may be related to the decreased methylation level of the INHBA gene promoter." (PMID 36304286, 2022). "However, the significance of INHBA expression in the prognosis of patients with breast cancer remains unclear." (PMID 36304286, 2022). "However, the biological roles of INHBA in breast cancer are still far to clear." (PMID 34889158, 2021). "Based on clinical evidence, we deduced that INHBA may affect breast cancer cell functions." (PMID 34889158, 2021). "However, little is known about the function of INHBA in breast cancer." (PMID 34889158, 2021).
breast carcinoma (continued). "To test this hypothesis, we investigated whether concomitant overexpression of INHBA and IL13Rα2 in breast cancer patients can be a significant prognostic factor by separating patients based on combined high or low expression levels of IL13Rα2 and INHBA in each patient." (PMID 30805303, 2019). "Among them, the INHBA gene plays a role in the occurrence and progression of several types of cancer, such as adenocarcinoma and breast cancer; in CYP1A1KO cells the INHBA gene was actually up-regulated." (PMID 38528259, 2024). "In contrast, INHBA expression correlated positively with infiltration of CD8+ T cells in colorectal and breast cancer." (PMID 38329386, 2024). "By activating the TGF-β signaling pathway, INHBA can induce epithelial–mesenchymal transformation (EMT) and accelerate the motility of breast cancer cells." (PMID 37940978, 2023). "The second expressed higher levels of INHBA and CD142 and was able to differentiate more efficiently into myofibroblasts in a TGFβ-dependent manner, or to Myo-CAFs in the presence of breast cancer cells, as evidenced by expressions of αSMA and N-cadherin." (PMID 36009475, 2022). "Our results demonstrated that INHBA was significantly stimulated the proliferation, migration, invasion and EMT of breast cancer by activating Wnt/β-catenin pathway." (PMID 34889158, 2021). "INHA, INHBA, TGFBR3, and ENG also predicted patients’ response to anthracycline and taxane therapy in luminal A breast cancers." (PMID 33819300, 2021). "We next examined individual genes and find that in luminal A breast cancers ENG, TGFBR3, INHA, and INHBA, were better performing as compared to INHBB particularly for taxane or anthracycline based chemotherapy regimens." (PMID 33819300, 2021). "However, the function and potential mechanism of INHBA in breast cancer remains unclear." (PMID 34889158, 2021). "Similar results were observed in another breast cancer cell line MCF-7, where miR-218 also upregulated INHBA but downregulated INHBB expression." (PMID 30348200, 2018). "Upregulated genes like INHBA, PSMD2 and OLR1 play a crucial role in breast cancer (BC) which may bring us some similarities between HNSCC and BC." (PMID 39749326, 2024). "In addition, a high level of INHBA expression was significantly correlated with worse OS and RFS in breast cancer with positive lymph nodes." (PMID 36304286, 2022). "To test our hypothesis and investigate the possible mechanism of INHBA in regulating the invasion and EMT of breast cancer, we investigated the expression of the related mRNA and proteins in Wnt/β-catenin pathway." (PMID 34889158, 2021). "It is also notable that activins have well-established morphogen roles during normal development, and that previous work has reported increased INHBA/activin-A activity at the leading edge of HER2-positive breast tumors and that follistatin can suppress HER2-positive breast cancer metastasis." (PMID 34239043, 2021). "Interestingly, examining expression revealed that in the same luminal A breast cancers INHA, ENG and INHBA are less expressed in responders to pharmacological treatment while TGFBR3 is more expressed in these responder groups." (PMID 33819300, 2021). "In summary INHA, INHBA, TGFBR3, and ENG display clear discrepant profiles of expression among responders and non-responders to both anthracycline and taxane chemotherapy for distinct breast cancer subtypes, specifically luminal A, and serous ovarian cancer." (PMID 33819300, 2021). "Here, we demonstrate that INHBA depletion downregulates IL13Rα2 expression in metastatic breast cancer cells, whereas treatment with Activin A in non-metastatic cells increases its expression levels." (PMID 30805303, 2019). "Using publicly available gene expression data, we examined the expression patterns of FST and INHBA, a subunit of activin, in normal and cancerous breast tissue and the prognostic value of FST in breast cancer metastases, recurrence-free survival, and overall survival." (PMID 28583174, 2017).
breast carcinoma (continued). "However, in breast cancer, the role of INHBA is mixed and has not yet been fully elucidated." (PMID 34889158, 2021). "Furthermore, we show here that knocking down INHBA in metastatic breast cancer cells, decreased their migratory potential without affecting their proliferative capacity in vitro, delayed primary tumor growth formation and significantly suppressed formation of lung metastases in vivo." (PMID 30805303, 2019).